SLC9A3 (solute carrier family 9 member A3)
Description:
Plasma membrane Na(+)/H(+) antiporter. Exchanges intracellular H(+) ions for extracellular Na(+) in 1:1 stoichiometry, playing a key role in salt and fluid absorption and pH homeostasis (By similarity). Major apical Na(+)/H(+) exchanger in kidney and intestine playing an important role in renal and intestine Na(+) absorption and blood pressure regulation.
Synonyms: NHE-3; NHE3; DIAR8
Tractability: Small molecule: an approved drug acts on it; a structure with a bound ligand is known; a high-quality ligand is known; it belongs to a druggable protein family. Antibody: UniProt places it where antibodies can reach, with high confidence; its Gene Ontology location is reachable by antibodies, with high confidence; UniProt predicts a signal peptide or a membrane-spanning region; the Human Protein Atlas places it where antibodies can reach. PROTAC: a small molecule that binds it is known.
Target class: SLC superfamily of solute carriers; SLC09 family of sodium/hydrogen exchangers; Electrochemical transporter; Transporter
Chemical probes: TENAPANOR (high quality)
Gene: Protein-coding gene on chromosome 5 (470,456 to 524,449, reverse strand). Ensembl gene ENSG00000066230.
Subcellular location: Apical cell membrane; Cell membrane; Recycling endosome membrane; Early endosome membrane
Subcellular location (Human Protein Atlas): Plasma membrane
Pathways (Reactome):
Transport of small molecules: Sodium/Proton exchangers
Gene Ontology:
Molecular function: identical protein binding; phosphatidylinositol binding; protein binding; sodium:proton antiporter activity; PDZ domain binding; antiporter activity
Biological process: intracellular sodium ion homeostasis; regulation of intracellular pH; sodium ion import across plasma membrane; sodium ion transmembrane transport; monoatomic cation transport; proton transmembrane transport; regulation of pH; sodium ion transport; transmembrane transport
Cellular component: apical plasma membrane; cation-transporting ATPase complex; early endosome; early endosome membrane; extracellular exosome; plasma membrane; recycling endosome membrane; basolateral plasma membrane; brush border; brush border membrane; cell surface; membrane
Genetic constraint (gnomAD): Loss-of-function variants: 30 observed, 67.87 expected, observed/expected ratio (o/e) 0.44, 90% interval 0.33 to 0.6. The upper end of that interval is the gene's LOEUF score, 0.6, which puts it in group 2 of 6, group 1 being the genes least tolerant of losing a copy. Missense variants: 977 observed, 1,065.6 expected, observed/expected ratio (o/e) 0.92, 90% interval 0.87 to 0.97. Synonymous variants: 568 observed, 483.82 expected, observed/expected ratio (o/e) 1.17, 90% interval 1.1 to 1.26.
Homologues: Orthologues: chimpanzee SLC9A3 (99% identical), macaque SLC9A3 (91% identical), dog SLC9A3 (90% identical), rat Slc9a3 (89% identical), guinea pig SLC9A3 (89% identical), pig SLC9A3 (87% identical), mouse Slc9a3 (83% identical), rabbit SLC9A3 (78% identical), tropical clawed frog slc9a3 (72% identical), zebrafish slc9a3.1 (50% identical), zebrafish slc9a3.2 (47% identical), Drosophila melanogaster Nhe2 (42% identical), and 5 more. Paralogues in human: SLC9A5 (51% identical), SLC9A2 (36% identical), SLC9A1 (35% identical), SLC9A4 (32% identical), SLC9A6 (21% identical), SLC9A9 (20% identical), SLC9A7 (20% identical), SLC9A8 (17% identical), SLC9C1 (15% identical), SLC9C2 (14% identical).